MGC27382 (uncharacterized MGC27382 )
Gene: Long non-coding RNA gene on chromosome 1 (78,222,433 to 78,369,464, forward strand). Ensembl gene ENSG00000237413.
Diseases named in the same sentence as MGC27382 in open-access papers:
MGC27382 is named in the same sentence as 1 disease in open-access papers, as found by Europe PMC text mining. Sharing a sentence is not in itself a finding about the gene and the disease. The quoted sentences say what the papers report.
lung squamous cell carcinoma (1 paper, 2019). "The MGC27382 gene was previously reported to be a part of an endogenous RNA network that could serve as a prognostic biomarker for lung squamous cell carcinoma." (PMID 31892232, 2019).